IL12A (interleukin 12A)
Diseases named in the same sentence as IL12A in open-access papers (continued):
Sharing a sentence is not in itself a finding about the gene and the disease.
tumor (continued). "Within the tumor microbiome, Lactobacillus plantarum L168 and its metabolite, indole-3-lactic acid, enhance dendritic cell function by increasing histone acetylation at the IL12a enhancer region, thereby increasing IL-12a production." (PMID 41582215, 2026). "Notably, low mRNA levels of Il12a were observed in splenocytes from the tumor-bearing mice, whereas splenocytes from the naïve and p38-blockade groups exhibited high mRNA levels of Il12a." (PMID 41282257, 2025). "Additionally, I3PA promotes the production of IL12a by increasing the deposition of H3K27ac at the IL12a enhancer in dendritic cells, thereby enhancing the function of tumor-infiltrating CD8+ T cells." (PMID 40032852, 2025). "In addition, recent studies have suggested that 3-ILA enhances the enrichment of H3K27ac around the IL12a enhancer region and promotes the production of IL12a by dendritic cells (DCs), which, in turn, activates the anti-tumor activity of CD8+ T cells." (PMID 41459217, 2025). "IL-12A, a component of IL-35, may be responsible for stimulating tumor cells to produce angiogenic proteins." (PMID 39974277, 2025). "Besides, impressively decline in Th2 cytokines (interleukin (IL)−10, IL‐6, TGF‐β) and increase in Th1 cytokines (IL‐2, interferon (IFN)‐γ, IL‐12a) were noted in serums from tumor‐bearing mice post Pres and irradiation treatments." (PMID 37875395, 2023). "We then analyzed the associations between CXCL2 expression and classical macrophage phenotype markers of M0 (undifferentiated) (AIF1), M1 (anti-tumor) (IL12A, TNF, NOS2, PTGS2) and M2 (tumor-promoting) (IL10, CD163, TGFB1, CSF1R) in TCGA-LIHC cohort with Spearman’s rank correlation test." (PMID 36276119, 2022). "In GC, EBI3 and IL12A expression are strongly related to larger tumor size." (PMID 33064893, 2020). "Moreover, compared to TAMs from WT tumor-bearing mice, those from Ubr5−/− tumor-bearing mice exhibited higher levels of M1 macrophage markers (e.g., il12a, Ccr2) and lower levels of M2 markers (e.g., Cx3cr1, il10)." (PMID 33293516, 2020). "Moreover, the pro-inflammatory mediators IL6 and IL8 were significantly overexpressed in the tumours, while IL12A was significantly downregulated." (PMID 23570247, 2013). "Moreover, PepO significantly switched TAM to the tumoricidal M1 macrophage as reflected by a reduction in the expression of M2 markers Arg-1, CD206, Fizz-1, Ym1 and IL-10 while increasing the expression of M1 markers iNOS, IL-12a and IL-1β and promoted apoptosis of the tumor cells." (PMID 37925462, 2023). "IL-35 expression within the TME can promote primary tumor cell growth and metastatic colonization at a secondary site, signaling through a receptor composed of gp130 and IL-12Rβ2 to induce downstream Ebi3 and IL-12a transcription and the activation of a classical JAK-STAT signaling pathway." (PMID 34093586, 2021). "In agreement with the expression pattern of EBI3 and IL12A found in public scRNA-seq tumor datasets, TCGA analysis revealed a positive correlation between EBI3 and IL12A in the majority (20 out of 32) of cancers from the TCGA database." (PMID 40610398, 2025). "The results demonstrated significantly higher mRNA expression of IFN-γ, TNF-α, IL-2, IL-12a, CXCL9, and CXCL10 in the tumor tissue of the PD-L1-KO/ZG16 overexpression group compared to the control group." (PMID 39958358, 2025). "The production of IL12a in dendritic cells was promoted by ILA by facilitating the increase in H3K27ac binding to IL12a enhancer regions, thereby aiding in the activation of CD8+ T cell (cytotoxic T lymphocyte, CTL) responses against tumor development." (PMID 40572223, 2025). "In relation to the increase in T cells, our results confirmed the induction of genes as Cd3g, Cd4, Il6, Il10 and Il12a in spleens of Ats1-KO mice, independently of the absence or presence of B16F1 tumours." (PMID 30166561, 2018).
tumor (continued). "By day 7, IFNγ, CSF2, CXCL10, GZMB, PTGS2, TNFα, CD80, CCL22, IL12a, IL13, IL1b, IL6, NOS2, and CTLA4 were significantly upregulated in the tumor-bearing mice bladders and AGTR2 and GATA3 were downregulated." (PMID 22013484, 2011). "Recently, the IPI‐based immune prognostic model based on eight genes including IL12A had independent prognostic significance in DLBCL patients, which provided an immunological perspective for elucidating the tumor progression mechanism of DLBCL, and were also useful for DLBCL immunotherapy." (PMID 37329186, 2023). "In addition, observably increased Th1 cytokines (IFN‐γ, IL‐12a and IL‐2) and decreased Th2 cytokines (IL‐6, IL‐10 and TGF‐β) in serums were also detected in tumor‐bearing mice post Pres and irradiation treatments." (PMID 37875395, 2023). "Moreover, the results of the immune checkpoint analysis showed that NOL7 expression in most tumor tissues was positively correlated with C10orf54, CD276, IL12A, and especially HMGB1." (PMID 36077008, 2022). "The IL12A AA haplotype included rs583911 and rs568408 and was an independent predictor of worse survival, together with the follicular patterns of T-cells (FOXP3+ and CD8+) and high IL-17F tumor levels." (PMID 32913559, 2020). "Likewise, immune-related genes such as Cd3g and Il12a appeared altered in a similar manner on the Ats1-KO background, independently of the presence of B16F1 tumours and in line with the increase in T cells observed by flow cytometry." (PMID 30166561, 2018). "The observed upregulation of IL6 and IL8 and downregulation of IL12A were therefore probably due to tumour-specific immunological responses that were independent of the presence of HPV." (PMID 23570247, 2013).
infection (46 papers, 2008 to 2025). The state of being infected such as from the introduction of a foreign agent such as serum, vaccine, antigenic substance or organism. "In this study, the associated genes (IFIH1, IFNB1, DDX58, CXCL10 and IL12A) in the RIG-I-like receptor signaling pathway were increased obviously at 8 h post-infection(p<0.05), compared to 3 h post-infection." (PMID 28938587, 2017). "We found the expression of il23a (encoding IL23p19) to be transiently upregulated on day 3 post infection (PI), alongside il12b (encoding IL12p40), while il12a (encoding IL12p35) was induced only by day 6 PI." (PMID 25761673, 2015). "Conversely, Pad2−/− mice showed a downregulation of M1‐related genes (Il1a, Il1b, Tnf, Cxcl2, Ccl4, Il12a, Cxcl1, Il6) compared to WT mice after PA infection." (PMID 40087815, 2025). "In contrast, treatment with αT induced higher IL-12A levels in Lb. rhamnosus (117 pg/mL) and Lc. lactis (115 pg/mL) infections than in the control, but a lower IL-12A level for Lb. paracasei infection (45 pg/mL)." (PMID 40873569, 2025). "Cluster 0 myeloid cells emerged as a prominent population post‐PA infection, characterized by the expression of Il12a, Il1a, Ccl4, and Csf3 genes, indicative of a pro‐inflammatory M1‐like phenotype." (PMID 40087815, 2025). "A few genes, namely il1b, il12a, cxl34a.4, saa, irg1l, mmp9 and cebpb, were significantly upregulated by infection in the common 151 signature set." (PMID 35933481, 2022). "A similar increase in each infection status group was observed for IL-12A secretion following addition of 1,25(OH)2D3 (P < 0.01)." (PMID 35111692, 2021). "While some expression patterns remained elevated during infection, by day 5 there was increased Il-12a, Il-12b, Il-6, Cd80, and Cxcl11 expression that corresponded with elevated Il-15 levels in young adult H1N1 and H3N2 infected lung." (PMID 34829979, 2021). "The expression of mRNA encoding several interleukins was also induced in the infected mouse uterus at 28 days post-infection, including Il1b, Il12a, Il12b, Il16, Il18, and Il27." (PMID 26779389, 2015). "There was little change in the mRNA levels for the Th1 cytokines, IL-12a and IL-12b, except in the bone marrow where levels were reduced following infection." (PMID 26244502, 2015). "Both genes encoding IL-12 had significantly increased transcript levels at the site of infection in our model (Il-12a Day 1 LFC 2.84; Day 4 LFC 2.00; Il-12b Day 4 LFC 2.23, Day 7 LFC 4.29)." (PMID 25901897, 2015). "In our results, mRNA for Il12 subunit alpha (Il12a) and subunit beta (Il12b) was induced at 28 days after infection." (PMID 26779389, 2015). "While e.g. IL12B expression was increased right after infection and throughout the entire experiment, IL10 and IL12A showed lower expression in early infection stage compared to E. coli K12 stimulated MDMs (P<0.005, unpaired t test)." (PMID 21629653, 2011). "Further investigation into IL-12A and IL-23 expression would be valuable to confirm whether both cytokines are induced during infection." (PMID 40463373, 2025). "We found that many cytokines messenger RNAs (mRNAs), including Il1b, Il5, Il6, Il10, Il12a/Il12p70, Ifng, Ccl4, Ccl5, Tnfa, Gcsf, Cxcl1, Il1a, and Il3, were significantly induced upon B.1.351 infection in the lungs of hACE2 transgenic, BALB/c, and C57BL/6 mice." (PMID 34907154, 2021). "In addition, Nc-Spain1H infection upregulated the IL12A and IL8 pro-inflammatory cytokines, whereas IL23 was downregulated by high virulent Nc-Spain7." (PMID 32711550, 2020). "Co-colonization of ASF-associated mice with SFB induced higher expression of pro-inflammatory cytokines such as Tnfα, Il1β, and Il12a upon MNV infection compared to infected ASF-associated mice without SFB." (PMID 31396223, 2019). "We found the upregulation of IL-12A, IL-12B, and TNF, suggesting a possible involvement of B cells in shaping the splenic type-1 cytokine environment in Ot infection." (PMID 37146079, 2023).
infection (continued). "In this study, we found that E. ictaluri EseN modulates the host immune response by increasing IL-8 and IL-15, and reducing IL-12a and IL-6 cytokines during HKDM infection." (PMID 35889053, 2022). "Significant upregulation of IL-12a was also detected in HKDM-∆EseN mutant compared to HKDM-WT during 1 h and 3 h, of post-infection." (PMID 35889053, 2022). "Thus, we determined whether local C5aR1 activation affects the transcription of IFN-γ (Ifng) in the spleen and brain as well as IL-12p35 (Il12a), IL-12p40 (Il12b), IL-18 (Il18), and iNOS (Nos2) in the brain of T. gondii-infected animals on day seven after infection using RT-qPCR." (PMID 32733463, 2020). "Consistent with this, il12a, il12b, ifng, il6, il17a mRNA expression were considerably increased in the brains of P. berghei ANKA-infected Alox5-KO vs. WT mice at 5 days after infection." (PMID 23613965, 2013). "The inflammatory gene profiles showed up-regulation during infection of eight genes, including IFNG and IL12A, which indicated an antiviral response." (PMID 18398488, 2008). "When Lb. rhamnosus and Lc. lactis infections were treated with GA at a subinhibitory concentration, IL-12A levels decreased dramatically, whereas no significant reduction was observed for Lb. paracasei infection." (PMID 40873569, 2025). "Our panel showed positive IFN-β, IL-12A, IL-1β and TNF-α immunostaining in the tissues of squirrel monkeys, demonstrating a similar profile in the nervous tissues of the newborns in G1, who were born after maternal infection." (PMID 33731800, 2021). "In the brains of PD-L1−/− mice a number of upstream regulators were enriched during acute infection but reduced or below threshold during persistent infection (e.g., IFN-γ, IL-15, NOS, NFATC2, and IL12-A), suggesting dynamic epigenetic changes in these genes in the absence of PD-1 signaling." (PMID 31105690, 2019). "Infection of SCC-25 cells with P. gingivalis W83 for 24 h induced up-regulation of genes also with biological functions in TLR signaling, the NF-κB pathway and MAPK downstream pathway, as well as the cytokine IL-12A." (PMID 28056810, 2017). "Gene expression analysis demonstrated a strong upregulation of IL23A (encodes p19) by infection, whereas IL23R, Epstein–Barr virus-induced gene 3 (EBI3), IL6ST, IL12A, and IL27RA were found to be expressed, but not regulated, or to a lesser extent." (PMID 24069393, 2013). "Finally, no significant alterations were found in IL12A after infection in both cell lines (P>.05)." (PMID 24069393, 2013). "We measured IL12A and IL10 mRNA levels in THP-1 cells treated with or without GM-CSF prior to infection with Legionella or stimulation with Pam3CSK4." (PMID 40470942, 2025). "During 5 h of infection, we were not able to detect expression of IL-12a from uninfected HKDM, IL-12a expression was detected only from HKDM-WT and ∆EesN while expression from HKDM-∆EseN was higher than from cells infected with WT." (PMID 35889053, 2022). "Therefore, we measured the secretion of pro-inflammatory (IL-8, IL-12a, IL-15, IL-6) cytokines by qPCR at different times after HKDM infection with WT and ∆EseN mutant, and uninfected HKDM as a negative control." (PMID 35889053, 2022). "However, IL12A and IL12B, which are thought to also favor Th1 cell development, did not change their expression level during infection." (PMID 18811943, 2008). "We used qPCR to analyze 12 host-related genes, including those with no significant fold change (IL12A), modest (e.g. TNF, LMO1, IL10, CCL2, IL1B) or high fold change, including CXCL8 which was among the 50 identified to be most significantly dysregulated in monocytes as a result of infection." (PMID 36747074, 2023).
cancer (21 papers, 2010 to 2025). A tumor composed of atypical neoplastic, often pleomorphic cells that invade other tissues. "The pooled analysis proved that IL-12A rs568408 polymorphisms was associated with overall cancer risk on allele comparison (A vs. G: OR = 1.18, 95%CI: 1.01-1.38, P = 0.04)." (PMID 28415696, 2017). "In the past years, we considered only IL-12B polymorphism played an important role in cancer development and looked down on the function of IL-12A." (PMID 28415696, 2017). "Among them, IL-6R, IL-8, IL-10RB, IL-12A, and IL-12B was significantly associated with the prognosis of cancer consistent to our finding." (PMID 25075970, 2014). "In the other types of cancer studies, IL-6R, IL-8, IL-10RB, IL-12A, and IL-12B genes were consistently associated with cancer prognosis between our study and theirs." (PMID 25075970, 2014). "The IL-6R, IL-8, IL-10RB, IL-12A, and IL-12B was associated with the prognosis of cancer in data of both our study and a previous study." (PMID 25075970, 2014). "Other genes include immune responses of T cells in cancer cells, insulin-receptor-related protein (INSRR), MHC II complex HLA-DQB and HLA-DQA, IL-12A, IL-20, glucose transporter 4 (GLUT4), insulinoma-associated protein 1 (INSM1), and insulin receptor (INSR)." (PMID 36769056, 2023). "Single Nucleotide Polymorphisms (SNP) in the IL-12 genes, IL12A and IL12B, have been reported to modulate cancer risk across different populations and cancer types." (PMID 32973967, 2020). "The gene expression data derived from the OSCC biopsies that showed upregulation of IL6 and IL8 and downregulation of IL12A were used to mimic inflammation in oesophageal epithelial and cancer as well as control cell lines." (PMID 23570247, 2013). "In cancer, SNPs in IL12A and IL12B may alter protein expression or function, contributing to immune dysregulation and increased oncogenic risk." (PMID 40519922, 2025). "IL-12A was reported to be an effective anti-cancer agent against various experimental malignancies." (PMID 39149564, 2024). "Only one meta-analysis (including eighteen studies) focused on IL-12A polymorphisms and suggested that both rs568408 and rs2243115 polymorphisms of IL-12A did not connect with cancer susceptibility." (PMID 28415696, 2017). "In fact, both IL-12A and IL-12B gene have played a role in the development of cancer." (PMID 28415696, 2017). "Ultimately, 33 studies with 10,587 cancer cases and 12,040 cancer-free controls were elected in this meta-analysis to explored the relationship of IL-12A rs568408 (10 studies), IL-12A rs2243115 (9 studies), and IL-12B rs3212227 (30 studies) polymorphisms and cancer risk." (PMID 28415696, 2017). "IL-12A polymorphisms (rs2243115 and rs568408) were found no influence on overall cancer risk." (PMID 28415696, 2017). "Among them, HLA-DMB, HLA-DRA, IL12A, and IL12B, whose determinant role in cancer outcome as immune adjuvants has already been published, are found in the top 500 TG2 positively correlating genes." (PMID 35725560, 2022). "IL-35 neutralizing antibody (anti-IL-12A antibody) suppressed migration and invasion of PCA cancer in vitro." (PMID 33041668, 2020). "In the metastatic human cancer samples, mTAMs expressed higher levels of EBI3 and IL12A compared with peripheral blood monocyte-derived macrophages (PMMs)." (PMID 30218063, 2018). "Finally, to assess the clinical relevance of our findings, we performed a pan-cancer survival analysis of EBI3 and IL12A expression using the TCGA database including solid tumors only." (PMID 40610398, 2025).
bacterial infection (6 papers, 2012 to 2025). "Upregulation of IFN-γ and IL-12A expression in inflammatory cells in the breast stroma of PCM patients indicates that the adaptive immune response associated with bacterial infection—the Th1 immune response—plays a role in this disease." (PMID 41019090, 2025). "Altogether, these results indicate that TIRAP can influence IRF5-mediated TLR8 signaling also during bacterial infection, which is especially clear for the induction of IL-12A expression by GBS." (PMID 35884781, 2022). "The data presented in this study suggests intricate immune modulation of macrophage responses to bacterial infections, particularly in relation to TNF-α, IL-6, IL-10, and IL-12A cytokine profiles." (PMID 40873569, 2025). "Moreover, in one non-IL-35 study of bacterial infection-released endotoxin lipopolysaccharide (LPS)-activated monocytes, IL-12A expression rapidly increased, peaked at 12 hours and then dropped back to background levels after 24 hours." (PMID 22438968, 2012).
infectious disease (2 papers, 2020 to 2022). A disorder directly resulting from the presence and activity of a microbial, viral, or parasitic agent in humans. "As the SNPs of this study had not yet been evaluated on PCM patients, we also compiled previous reports on the IL18 (-607 C/A, rs1946518 and -137 G/C, rs187238), IL12A (-504 G/T, rs2243115), and IFNGR1 (-611 A/G, rs13277474) SNPs and their association with diverse infectious diseases (respectively)." (PMID 33117339, 2020).
inflammation (2 papers, 2013 to 2021). Aberrant reaction of the microcirculation characterized by movement of fluid and leukocytes from the blood into extravascular tissues. "Several genes that are involved in mucosal protection and immunity, such as Cxcl2 and IL-12A, retain levels of expression that are comparable to those observed in WT C57BL/6 mice and Lcn2, a gene that has been associated with gut inflammation, was detected at higher levels in Casp1−/− mice." (PMID 23977202, 2013).
cardiovascular diseases (1 paper, 2021). "Evidence suggests that Il12a participates in the regulation of various cardiovascular diseases and exhibits very different biological activities, including pro-inflammatory and anti-inflammatory activities." (PMID 34276358, 2021). "IL-12p35 (Il12a) is a common component of IL-12 and participates in the regulation of various cardiovascular diseases." (PMID 34276358, 2021).